ESPL1 (extra spindle pole bodies like 1, separase)
Description:
Caspase-like protease, which plays a central role in the chromosome segregation by cleaving the SCC1/RAD21 subunit of the cohesin complex at the onset of anaphase. During most of the cell cycle, it is inactivated by different mechanisms.
Synonyms: ESP1; KIAA0165; SEPA
Tractability: PROTAC: ubiquitination databases record sites on it.
Target class: Enzyme; Hydrolase
Gene: Protein-coding gene on chromosome 12 (53,268,285 to 53,293,643, forward strand). Ensembl gene ENSG00000135476.
Subcellular location: Cytoplasm; Nucleus
Subcellular location (Human Protein Atlas): Nucleoplasm; Vesicles
Pathways (Reactome):
Cell Cycle: Separation of Sister Chromatids
Gene Ontology:
Molecular function: protein binding; catalytic activity; cysteine-type endopeptidase activity; cysteine-type peptidase activity; peptidase activity
Biological process: mitotic sister chromatid segregation; apoptotic process; establishment of mitotic spindle localization; maintenance of meiotic sister chromatid cohesion; maintenance of mitotic sister chromatid cohesion; mitotic cytokinesis; mitotic sister chromatid separation; negative regulation of sister chromatid cohesion; positive regulation of mitotic metaphase/anaphase transition; nuclear chromosome segregation; nuclear division; proteolysis
Cellular component: centrosome; nucleoplasm; separase-securin complex; cytoplasm; cytosol; mitotic spindle; nucleus
Genetic constraint (gnomAD): Loss-of-function variants: 50 observed, 216.99 expected, observed/expected ratio (o/e) 0.23, 90% interval 0.18 to 0.29. The upper end of that interval is the gene's LOEUF score, 0.29, which puts it in group 1 of 6, group 1 being the genes least tolerant of losing a copy. Missense variants: 1,800 observed, 2,656.7 expected, observed/expected ratio (o/e) 0.68, 90% interval 0.65 to 0.7. Synonymous variants: 978 observed, 1,108.7 expected, observed/expected ratio (o/e) 0.88, 90% interval 0.84 to 0.93.
Homologues: Orthologues: chimpanzee ESPL1 (99% identical), macaque ESPL1 (96% identical), pig ESPL1 (85% identical), rabbit ESPL1 (83% identical), dog ESPL1 (82% identical), guinea pig ESPL1 (81% identical), rat Espl1 (78% identical), mouse Espl1 (77% identical), tropical clawed frog espl1 (42% identical), zebrafish espl1 (34% identical), Caenorhabditis elegans sep-1 (11% identical), Caenorhabditis elegans ZK430.5 (10% identical), and 1 more.
Diseases named in the same sentence as ESPL1 in open-access papers:
ESPL1 is named in the same sentence as 58 diseases in open-access papers, as found by Europe PMC text mining. Sharing a sentence is not in itself a finding about the gene and the disease. The quoted sentences say what the papers report.
breast carcinoma (15 papers, 2015 to 2025). "While the transcriptional regulation of ESPL1 in breast cancer (BC) is increasingly understood, the mechanisms underlying its aberrant upregulation remain incompletely elucidated." (PMID 41268575, 2025). "In luminal breast cancers, the increased expression of ESPL1 was associated with poor prognosis of patients of the luminal B subtype." (PMID 36359523, 2022). "Studies have shown that higher ESPL1 expression was associated with poor prognosis and advanced stage in luminal B breast cancers, and it as a candidate oncogene for BRCA." (PMID 35814478, 2022). "By integrating transcriptomic, ceRNA network, and docking-based findings, our study provides a multi-dimensional framework positioning ESPL1 as both a prognostic biomarker and a potential therapeutic target in breast cancer." (PMID 41268575, 2025). "To investigate the functional relevance of ESPL1 in breast cancer (BC), we explored its involvement in key oncogenic processes using the CancerSEA database." (PMID 41268575, 2025). "It was reported that ESPL1 was overexpressed in different malignant tumors, such as breast cancer and glioma and ESPL1 was shown to have oncogenic activity in mouse model." (PMID 38402402, 2024). "Increasing evidence indicates that ESPL1 participates in cell cycle signalling in breast cancer, endometrial cancer (UCEC) and HCC, thus promoting the proliferation and migration of cancer cells." (PMID 38813236, 2024). "Several studies have shown that ESPL1, as a candidate oncogene, is overexpressed in several types of breast cancers." (PMID 33282948, 2020). "This research is significant in revealing the etiology of breast cancer by elucidating the function of ESPL1, which may provide a potential molecular marker for the diagnosis and treatment of breast cancer, particularly concerning its aggressiveness." (PMID 41268575, 2025). "Together, these results suggest that E2F7 and E2F8 may act as critical upstream transcriptional regulators of ESPL1, potentially promoting its overexpression in aggressive subtypes of breast cancer." (PMID 41268575, 2025). "To further investigate the expression pattern of ESPL1 across various breast cancer (BC) subtypes, we utilized the bc-GenExMiner v5.0 database, stratifying the data based on estrogen receptor (ER), progesterone receptor (PR), and triple-negative breast cancer (TNBC) status." (PMID 41268575, 2025). "Together, these findings implicate hsa-let-7b-5p as a critical post-transcriptional regulator of ESPL1 and highlight a potential ceRNA network involving hsa-let-7b-5p, E2F8, and ESPL1 that may drive tumor progression and poor prognosis in breast cancer." (PMID 41268575, 2025). "Equally, ESPL1 was proven to be a cancer oncogene for breast cancer." (PMID 32170852, 2020). "In addition, overexpression of the ESPL1 separase protease (another E2F target gene) was observed upon TCEAL1 knockdown; ESPL1 is implicated to increase aneuploidy in a murine breast cancer model." (PMID 33033111, 2020). "However, ESPL1/separase has been recognized as a putative oncogene of luminal B breast cancers." (PMID 36359523, 2022). "Indeed, there were 5 genes that were present in our list and in the up regulated list for breast cancer (RAP2C, SPN, GINS2, ESPL1 and IRF7)." (PMID 29108258, 2017). "In contrast, ESPL1 functions as an oncogene rather than as an antioncogene in breast cancer." (PMID 31828101, 2019).
endometrial cancer (8 papers, 2020 to 2025). Primary or metastatic malignant neoplasm involving the endometrium (mucous membrane that lines the endometrial cavity). "Our findings corroborate previous studies that have implicated TPX2, BUB1, and ESPL1 in the development and progression of endometrial cancer." (PMID 39596419, 2024). "Various cancer types, including BC, bladder cancer, esophageal carcinoma, gastric cancer, liver cancer, lung cancer, and endometrial cancer, exhibit elevated ESPL1 expression." (PMID 41268575, 2025). "Studies reported that ESPL1 was elevated in endometrial cancer, and its higher expression correlated with late stage and higher tumor grade." (PMID 35814478, 2022). "Previously, several studies have reported that ESPL1 mainly enriched in the cell cycle pathway in endometrial cancer." (PMID 35814478, 2022). "ESPL1 expression was found to be increased in endometrial cancer (EC) tissues, but the clinical significance and functional mechanism of ESPL1 in EC remains to be verified." (PMID 34143800, 2021). "ESPL1 is involved in sister chromatids separation during anaphase and its oncogenic activity was found in BC and endometrial cancer." (PMID 32932728, 2020). "In addition, abnormal expression of ESPL1 in endometrial cancer (EC) facilitates metastasis and invasion, leading to a poor prognosis." (PMID 41268575, 2025).
lung carcinoma (7 papers, 2021 to 2025). "The overexpression of Espl1 has been reported to be associated with augmented malignancy in lung cancer." (PMID 39273313, 2024). "Results suggested that upregulated ESPL1 expression was associated with adverse clinical outcomes in patients with lung cancer." (PMID 35814478, 2022). "ESPL1 has also been implicated in the increased malignancy of both non-small cell and small cell lung cancer, positioning it as a potential target for molecular therapy in lung cancer." (PMID 41268575, 2025). "In the present study, the relationship between extra spindle pole bodies like 1 (ESPL1) and Timeless and their expression in lung cancer was further studied." (PMID 36359523, 2022). "In our study, we confirmed that ESPL1 was upregulated in lung cancer and cell lines, which is consistent with the online database we discovered." (PMID 35814478, 2022). "First, the present study only explored the expression levels and prognostic potential of the Timeless and ESPL1 genes in lung cancer using several public databases." (PMID 36359523, 2022). "In the cBioPortal and GEPIA database analyses, extra spindle pole bodies like 1 (ESPL1) was the top correlated gene of Timeless in patients with lung cancer." (PMID 36359523, 2022). "IHC assay confirmed that ESPL1 was upregulated in lung cancer tissues compared with normal lung tissues." (PMID 35814478, 2022). "Finally, we further validated the dysregulated expression of ESPL1 by comparing it with eight independent GEO datasets, including cervical cancer, lung cancer, liver cancer, and colorectal cancer." (PMID 37006282, 2023). "The prognostic potential of ESPL1 was similar to that of the Timeless gene in lung cancer." (PMID 36359523, 2022). "Moreover, IHC results confirmed that ESPL1 was upregulated in lung cancer tissues compared with normal lung tissues." (PMID 35814478, 2022). "In addition to lung cancer, studies also indicated that ESPL1 and five other genes were significantly upregulated in small cell lung carcinoma as compared to normal cells, lung squamous cell carcinoma, lung adenocarcinoma and large cell carcinoma." (PMID 36359523, 2022). "Altogether, these results suggested that the Timeless gene and its co-expressed ESPL1 gene may have great prognostic and treatment potential in lung cancer." (PMID 36359523, 2022). "In addition, it has been reported that enhanced ESPL1 expression might be the reason for the increased malignancy of non-small cell and small cell lung cancer, and that ESPL1 represents a potential target for molecular therapy of lung cancer." (PMID 34512713, 2021).
bladder cancer (5 papers, 2019 to 2025). "This study aimed to explore the expression level and transcriptional regulation mechanism of Extra Spindle Pole Bodies Like 1 (ESPL1) in bladder cancer (BC)." (PMID 38813236, 2024). "have found that STAG2, ESPL1 and NIPBL genes with frequent mutations in bladder cancer are involved in the SCCS process." (PMID 34094968, 2021). "STAG2, ESPL1 and NIPBL genes with frequent mutations in bladder cancer are involved in the sister chromatid cohesion and segregation process." (PMID 34094968, 2021).
glioma (5 papers, 2021 to 2024). A benign or malignant brain and spinal cord tumor that arises from glial cells (astrocytes, oligodendrocytes, ependymal cells). "It has been confirmed that ESPL1 was overexpressed in glioma and associated with the pathological features and poor prognostics in glioma patients." (PMID 35814478, 2022). "In summary, these results indicate that ESPL1 has diagnostic significance for patients with glioma, especially for low-grade gliomas." (PMID 34512713, 2021). "Our results demonstrated that upregulation of ESPL1 is associated with poor prognosis in glioma patients." (PMID 34512713, 2021). "It is worth noting that the expression level of ESPL1 has good diagnostic value among various molecular subtypes in the molecular typing of gliomas." (PMID 34512713, 2021). "To determine whether high expression of ESPL1 has clinical diagnostic value for the prognosis of glioma, we used Cox regression and Kaplan–Meier methods to draw ROC curves of the CGGA RNA-seq, CGGA microarray, and TCGA RNA-seq cohorts." (PMID 34512713, 2021). "In addition, ESPL1 expression was considerably associated with the clinical and pathological features of gliomas, such as World Health Organization grade, histology, and 1p19q co-deletion status." (PMID 34512713, 2021). "In addition, in the grading of gliomas, these independent datasets consistently showed that the expression level of ESPL1 has good diagnostic value for the prognosis of low-grade gliomas." (PMID 34512713, 2021). "Based on the role of ESPL1 in other tumors, we speculate that ESPL1 might be associated with the clinical features and survival prognosis of glioma patients." (PMID 34512713, 2021). "In addition, univariate and multivariate Cox analyses demonstrated that ESPL1 expression might be a useful biomarker for glioma prognosis and that ROC analysis confirmed the diagnostic value of ESPL1 expression in glioma." (PMID 34512713, 2021). "Research has shown that ESPL1 is involved in the development and progression of several types of cancer, including glioma, breast, stomach, bladder, liver, and endometrial cancers." (PMID 39093763, 2024). "Next, to further examine the effects of abnormally high expression of ESPL1 on the prognosis of glioma, we analyzed three data cohorts: CGGA RNA-seq, CGGA microarray, and TCGA RNA-seq and created survival curves." (PMID 34512713, 2021). "Although this study utilized multiple datasets with thousands of glioma samples for scientific analysis, revealing the mechanism of ESPL1 in glioma diagnosis and treatment will require additional studies." (PMID 34512713, 2021). "These signaling pathways have been shown to play key roles in the biological behavior of many tumors in terms of metastasis and proliferation, indicating the potential role of ESPL1 as a new therapeutic and prognostic biomarker in glioma." (PMID 34512713, 2021). "This study plays an important role in revealing the etiology of glioma by revealing the function of ESPL1, providing a potential molecular marker for the diagnosis and treatment of glioma, especially low-grade glioma." (PMID 34512713, 2021). "The results demonstrated that ESPL1 expression in glioma tissues was elevated compared to that in normal brain tissues at both the mRNA and protein levels." (PMID 34512713, 2021). "In these three datasets, the expression levels of ESPL1 in glioma tissues were significantly higher than those in corresponding normal tissues." (PMID 34512713, 2021). "In summary, our results suggest that the overexpression of ESPL1 is closely related to poor prognosis in glioma patients." (PMID 34512713, 2021). "Univariate Cox analysis demonstrated that increased ESPL1 expression in glioma was closely related to poor prognosis in CGGA RNA-seq (HR = 1.633), CGGA microarray (HR = 2.050), and TCGA RNA-seq (HR = 1.353)." (PMID 34512713, 2021).
glioma (continued). "Elucidating the expression levels of ESPL1 in glioma and its clinical relevance will help to establish a new therapeutic target to improve existing treatment methods." (PMID 34512713, 2021). "In this study, we first assessed the expression levels of ESPL1 in glioma using the GEPIA, GEO, and HPA databases." (PMID 34512713, 2021). "To verify the expression of ESPL1 in normal brain and glioma tissues at the protein level, we downloaded six immunohistochemical slices from the HPA7 (two normal, two low-grade, and two high-grade), which were stained with HPA073188." (PMID 34512713, 2021). "Results showed that ESPL1 protein expression levels in glioma tissue samples were significantly higher than those in normal brains." (PMID 34512713, 2021). "Thereafter, to understand the changes in ESPL1 expression in glioma tissues at a deeper level, we performed analysis on three glioma-related GSE datasets (GSE2223, GSE4290, GSE50161) from the GEO database, including 40 normal brain and 161 glioma samples." (PMID 34512713, 2021). "The results demonstrated that the mRNA and protein levels of ESPL1 in glioma were higher than those in normal brain tissues." (PMID 34512713, 2021). "The results revealed that ESPL1 was markedly overexpressed in glioma cell lines compared to that in HAs." (PMID 34512713, 2021). "It has been confirmed that ESPL1 was highly expressed as a prognostic biomarker in glioma and LIHC." (PMID 35814478, 2022). "Furthermore, there was a direct relationship between higher glioma grade and higher expression levels of ESPL1." (PMID 34512713, 2021). "Moreover, Kaplan–Meier curves for OS showed that higher expression of ESPL1 was related to worse outcomes in glioma patients, especially in patients with low-grade gliomas." (PMID 34512713, 2021). "These genes also indirectly suggest that ESPL1 may promote the pathological processes of glioma and affect the prognosis of glioma patients." (PMID 34512713, 2021). "Therefore, further studies on the mechanism of ESPL1 in glioma are needed to clarify and expand upon these findings." (PMID 34512713, 2021). "However, for the prognosis of low-grade gliomas, the increased expression of ESPL1 can indeed reduce the OS time of patients." (PMID 34512713, 2021). "Finally, reverse transcription-quantitative polymerase chain reaction (RT-qPCR) was used to detect the expression levels of ESPL1 in glioma cell lines." (PMID 34512713, 2021). "Importantly, ESPL1 reduced the overall survival (OS) of glioma patients and had prognostic value for gliomas." (PMID 34512713, 2021). "Therefore, it is reasonable to speculate that ESPL1 may represent a novel and reliable biomarker for glioma and may aid in the development of individualized treatment strategies." (PMID 34512713, 2021). "However, the relationship between ESPL1 and glioma has not yet been demonstrated." (PMID 34512713, 2021). "However, there is no literature on the relationship between ESPL1 and glioma." (PMID 34512713, 2021). "However, the regulatory mechanisms of ESPL1 in gliomas has not yet been studied." (PMID 34512713, 2021).
hepatocellular carcinoma (5 papers, 2022 to 2025). A malignant tumor that arises from hepatocytes. "There is growing evidence that high expression of ESPL1 is strongly associated with the development of malignant tumours, such as hepatocellular carcinoma (HCC), glioma, lung adenocarcinoma (LUAD) and colorectal cancer (CRC)." (PMID 38813236, 2024).
gastric adenocarcinoma (4 papers, 2019 to 2022). "Furthermore, the expression level of ESPL1 was negatively associated with the pathologic stage/progression of gastric adenocarcinoma." (PMID 36359523, 2022). "ESPL1 expression was negatively correlated with gastric adenocarcinoma pathologic stage progression, and the high expression of ESPL1 was significantly correlated with favorable outcomes." (PMID 31828101, 2019). "Nevertheless, it has also been reported that ESPL1 plays an opposite role in gastric adenocarcinoma." (PMID 31105744, 2019).
mammary adenocarcinomas (4 papers, 2018 to 2025). "For example, overexpression of ESPL1 in the mammary glands of MMTV-ESPL1 mice causes them to form aggressive mammary adenocarcinomas with high levels of genetic instability, cell cycle defects, poor differentiation, distant metastasis and metaplasia." (PMID 41268575, 2025). "ESPL1, a protease (Separase) encoded gene, was reported overexpressing in mammary adenocarcinomas and related to tumor initiation and progression, but not mentioned in GAC." (PMID 29884122, 2018).
breast tumor (3 papers, 2010 to 2025). "Subsequent qRT-PCR-based gene expression profiling revealed a significant upregulation of ESPL1 mRNA in breast tumor tissues compared to their adjacent healthy counterparts, with an overall average increase of 4-fold." (PMID 41268575, 2025).